EIF2AK3 (eukaryotic translation initiation factor 2 alpha kinase 3)
Diseases named in the same sentence as EIF2AK3 in open-access papers (continued):
Sharing a sentence is not in itself a finding about the gene and the disease.
multiple epiphyseal dysplasia (4 papers, 2011 to 2021). Multiple epiphyseal dysplasias (MED/EDMs) are characterized by epiphyseal anomalies causing joint pain early in life, recurrent osteochondritis and early arthrosis. "Case 109 had EIF2AK3-related multiple epiphyseal dysplasia with early-onset diabetes mellitus (OMIM: 226980)." (PMID 34539730, 2021).
neutropenia (4 papers, 2013 to 2025). A decrease in the number of neutrophils found in the blood. "It is therefore difficult to conclude whether certain EIF2AK3 mutations are associated with neutropenia, at least in Saudi families with WRS." (PMID 23759358, 2013). "This clinical variability does not seem to be dependent on the EIF2AK3 mutation with the possible exception of older age and neutropenia." (PMID 30922274, 2019).
prediabetes (4 papers, 2020 to 2025). "The rs6750998 and rs17037621 are intron SNPs in EIF2AK3 and associated with insulin resistance, high BMI, and the risk of prediabetes." (PMID 35923704, 2022). "The rs867529 is a nonsynonymous SNP in EIF2AK3 and is correlated with the risk of prediabetes and lower bone mineral density." (PMID 35923704, 2022).
acute kidney injury (3 papers, 2013 to 2025). Sudden and sustained deterioration of the kidney function characterized by decreased glomerular filtration rate, increased serum creatinine or oliguria. "Although it is not reported in Eif2ak3 knockout mice, phenotypic features including severity and unexplained hypoglycaemic episodes are suggestive of hepatic impairment and renal failure." (PMID 24032041, 2013).
MODY (2 papers, 2018 to 2024). "Other rare variants found in a South Indian population that could potentially play a role in MODY pathogenesis are EIF2AK3, GLIS3, HADH, and PTF1A." (PMID 39201476, 2024).
asbestosis (1 paper, 2025). A lung disorder caused by inhalation of asbestos fibers. "Here, we show that ER stress resulted in protein kinase RNA-like ER kinase (PERK; Eif2ak3) activation in humans with asbestosis." (PMID 40208691, 2025).
B-cell neoplasm (1 paper, 2020). A group of heterogeneous lymphoid tumors generally expressing one or more B-cell antigens or representing malignant transformations of B-lymphocytes. "Next generation sequencing has revealed the presence of recurrent mutations of genes encoding several factors related to mRNA translation, including XPO1, DDX3X, RPS15 and EIF2AK3 (PERK) in mature B-cell neoplasms." (PMID 32924027, 2020).
developmental dysplasia of the hip (1 paper, 2026). A spectrum of hip abnormalities commonly presenting in infancy involving the relationship between the femoral head and the acetabulum and that includes subluxation or dislocation at rest or upon provocation. "One individual with a homozygous EIF2AK3 variant (rs1205989324, c.1650 + 1G > A) was diagnosed with Wolcott‒Rallison syndrome and presented with developmental dysplasia of the hip." (PMID 41498801, 2026). "We identified a homozygous EIF2AK3 variant (c.1650 + 1G > A, rs1205989324) in a patient with Wolcott‒Rallison syndrome (OMIM 226980) and developmental dysplasia of the hip." (PMID 41498801, 2026).
follicular carcinoma (1 paper, 2021).
medullary carcinoma (1 paper, 2021). "In radiation-induced medullary carcinoma in 4W rats, the expression of Cdkn2a and Cxcr4 increased, whereas that of seven autophagy regulatory genes (Dapk1, Eif2ak3, Gaa, Hgs, Mapkl4, Mapt, and Pim2) and five autophagy machinery components (Atg4b, Atg5, Gabarapl2, Rab24, and Wipi1) decreased." (PMID 34580369, 2021).
Osteochondrosis (1 paper, 2014). Abnormal growth ossification centers in children. "The EIF2AK3 gene overlaps with QTLs for osteochondrosis score and feet and leg conformation." (PMID 25030608, 2014).
tumor (624 papers, 2005 to 2026). "Hierarchical clustering revealed a distinct gene cluster associated with EIF2AK3 across several tumour types." (PMID 41880108, 2026). "Subsequent scRNA-seq analysis of malignant subpopulations (Ost_1 and Cho_2) revealed three key genes (GABARAP, BNIP3, EIF2AK3) consistently overexpressed in tumor cells and linked to poor outcomes." (PMID 41346635, 2025). "Gene Ontology (GO) enrichment analysis supported these observations, with high EIF2AK3 tumours displaying strong associations with cell adhesion, ECM structural remodelling and actin binding, while low EIF2AK3 tumours showed enrichment in cytoskeletal stability and axonogenesis." (PMID 41880108, 2026). "RESULTS: Transcriptomic analysis revealed EIF2AK3 upregulation in multiple cancers, with proteomic data supporting increased PERK protein levels in specific tumour types." (PMID 41880108, 2026). "EIF2AK3 expression was correlated with age, gender, tumour stage and survival endpoints in a context-dependent manner." (PMID 41880108, 2026). "EIF2AK3 knockdown significantly reduced tumor growth, an effect that was partially reversed by Rapa treatment." (PMID 41353169, 2025). "Immunohistochemistry confirmed efficient knockdown of EIF2AK3 in tumor tissues, which was mitigated by Rapa." (PMID 41353169, 2025). "Among the five identified ICDGs, NT5E, HSP90AA1, and EIF2AK3 exhibited heightened expression levels in tumor tissues, while PIK3CA and P2RX7 demonstrated elevated expression levels in normal tissues." (PMID 38575204, 2024). "The five-gene signature’s expression was validated utilizing the TCGA database, with NT5E, HSP90AA1, and EIF2AK3 demonstrating elevated expression levels in tumor tissues, while PIK3CA and P2RX7 exhibited heightened expression in normal tissues." (PMID 38575204, 2024). "Our in vitro experiments also confirmed that the expression level of EIF2AK3 elevated with an increase in tumor grade, and EIF2AK3 enhances the abilities of tumor cell proliferation and migration." (PMID 37153540, 2023). "In contrast, tumours with low EIF2AK3 expression demonstrated enrichment in focal adhesion, AGE-RAGE signalling and cytoskeletal organisation, suggesting a tumour state dependent on adhesion integrity and extracellular matrix (ECM) interaction rather than stress-induced plasticity." (PMID 41880108, 2026). "Kyoto Encyclopedia of Genes and Genomes (KEGG) pathway enrichment analysis revealed that the cell cycle, proteoglycans in cancer and focal adhesion pathways were among the most consistently enriched across tumour types, particularly in tumours with high EIF2AK3 expression." (PMID 41880108, 2026). "In addition, EIF2AK3 induces immune metabolic reprogramming and enhances anti-tumor T cell function." (PMID 36212143, 2022). "Early studies have shown that PERK (EIF2AK3) plays a role in tumor angiogenesis." (PMID 36178365, 2022). "Therefore, the dual characteristics of tumor inhibition and tumor promotion of EIF2AK3 still need to be further studied in CM." (PMID 36212143, 2022). "This confirmed that tumor cells secrete factors that induce mRNA-expression of EIF2AK3, DDIT3, HSPA5, spliced XBP1, and HSPA5, as well as protein expression of p-IRE1α in hepatic stellate cells co-cultured with tumor cells, indicating the presence of ER-stress." (PMID 33103995, 2020). "Results indicated that EIF2AK3 and POLG expression levels correlated with the TCR CDR3-DDX53 Combo CSs, consistent with a higher proliferation rate for the tumor cells representing the higher CSs and worse DFS probabilities." (PMID 37953875, 2023). "To address the first question, we correlated the microarray-based mRNA expression of the 5 CSA targets (EIF2AK3, MAPK12/p38γ, PAK1, RPS6KA3, and WNK3) in a panel of 60 tumor lines of the NCI, USA, with 83 standard anticancer agents." (PMID 35163434, 2022). "Three genes from the PERK pathway (EIF2S1, EIF2AK3, and DDIT3) showed a positive correlation with the SCNA score across almost every tumor type." (PMID 34698427, 2021).
tumor (continued). "We also integrated the macrophage score with ERN1 and EIF2AK3 to predict CD274 expression in an ordinary least squares (OLS) linear regression model, including the tumor type as a covariate." (PMID 32520957, 2020). "Indeed, myeloid cell-conditional Eif2ak3−/− mice (Eif2ak3fl/fl; Lyz2-cre) that possess abrogated PERK exhibit functional reprogramming of M-MDSCs and PMN-MDSCs and also overexpression of anti-tumour cytokines and tumour growth arrest." (PMID 34685679, 2021). "(A) mRNA expression of ER-stress markers Edem1, Ero1b, Grp94, Herp, Atf4, Eif2ak3, Ddit3, and Hspa5 in liver tissue from healthy mice; and tumor tissue and surrounding non-tumoral tissue from mice with DEN-induced HCC." (PMID 33103995, 2020). "By co-culturing stellate cells with tumor cells, we mainly observed an increase of the IRE1α-branch of the UPR; however, it is important to note that HepG2-cells also significantly induced mRNA-expression of EIF2AK3, while Huh7-cells seemed to induce DDIT3 in the LX2-cells." (PMID 33103995, 2020).
cancer (444 papers, 2009 to 2026). A tumor composed of atypical neoplastic, often pleomorphic cells that invade other tissues. "CONCLUSION: These findings underscore the central role of EIF2AK3/PERK in regulating cancer-associated pathways." (PMID 41880108, 2026). "For the remaining three genes with Coef less than 0 in the risk score, EIF2AK3 (Eukaryotic Translation Initiation Factor 2 Alpha Kinase 3), which encodes a membrane protein, silencing in cancer cells prevents ERS and induces apoptosis." (PMID 37328788, 2023). "Significantly, EIF2AK3/PERK signalling has previously been linked to the resistance of cancer cells to multiple anticancer chemotherapeutic agents, including drugs that target the ubiquitin/proteasome pathway and taxanes." (PMID 22253692, 2012). "Development of next generation EIF2AK3 inhibitors or ERN1 inhibitors may yield selective agents which can directly modulate the UPR in cancer-associated bone disease." (PMID 40877255, 2025). "EIF2AK3 (PERK), a central UPR regulator, has been implicated in chemoresistance across multiple cancer types." (PMID 41353169, 2025). "EIF2AK3 (eukaryotic translation initiation factor 2 alpha kinase 3), also called protein kinase PERK, is a transducer of unfolded protein responses implicated in endoplasmic reticulum stress, contributing to cancer development." (PMID 35611939, 2022). "When exposed to paclitaxel, cancer cells activated the EIF2AK3/EIF2AK4‐pEIF2S1‐ATF4 axis and maintained redox homoeostasis by inducing expression of the major antioxidant enzymes HMOX1, SHMT2 and SLC7A11." (PMID 31211507, 2019). "Together these observations clearly indicate the critical involvement of EIF2AK3/PERK in the phosphorylation of EIF2A, cyclin D loss and the attenuation of pRB phosphorylation seen in CCT020312-treated cancer cells." (PMID 22253692, 2012). "The interaction of RFX6 with other upregulated genes, such as EIF2AK3, may induce a severe diabetic condition and could be related to multi-organ impairment and cancer degeneration." (PMID 34715892, 2021). "Correlation analysis using transcriptomic data from the TCGA database revealed that RPN1 expression positively correlates with the ER stress-related genes PERK (EIF2AK3) and ATF6 in multiple cancer types." (PMID 39749324, 2024). "Reciprocal regulation between EIF2AK3 and EIF2AK4 through the JNK–FOXO3 axis modulates cancer drug resistance and clonal survival." (PMID 35954244, 2022). "(A) mRNA-expression of ER-stress markers ATF6, ATF4, EIF2AK3, GADD34, EDEM1, DDIT3 and HSPA5, in stellate cells (LX2) co-cultured with cancer cells (HepG2 or Huh7) and treated with 4μ8C or control." (PMID 33103995, 2020). "Thus, eukaryotic translation initiation factor 2-alpha kinase 3 (EIF2AK3, best known as PERK) and the ER-to-Golgi secretory machinery are considered “core” signaling components on the cancer cell side." (PMID 26635802, 2015). "UPR effectors, including ERN1 (IRE1α), ATF6, and PERK (EIF2AK3), dissociate from HSPA5 (GRP78) and activate their respective canonical targets (XBP1s, ATF6α, and ATF4); subsequently trigger transcriptional reprogramming that promotes the survival of cancer cells under ER stress." (PMID 40821803, 2025). "Previous studies in Drosophila have shown that GCN2 (eIF2AK4) and PERK (eIF2AK3) can cooperate to modulate FOXO activity in response to ER stress, suggesting the PERK-related GCN2 can potentially compensate for the inactivation of PERK function in cancer cells." (PMID 32615282, 2020). "Indeed, recent research has shown that PERK (PKR-like endoplasmic reticulum kinase, also called eukaryotic translation initiation factor 2-alpha kinase 3 (EIF2A3K)) is regulated by FOXO3 and thus exposed a transformed cell and chemotherapeutic drug–resistant cancer cell vulnerability in PERK." (PMID 32372224, 2020).
infection (157 papers, 2009 to 2025). The state of being infected such as from the introduction of a foreign agent such as serum, vaccine, antigenic substance or organism. "Additionally, the top predicted transcriptional regulators (P < .01) at 2 h post-infection of the pre-treated cells were dextran sulfate, TLR4, kinase EIF2AK3, FCGR2A, and LEP." (PMID 33382951, 2021).
neurodegenerative disease (55 papers, 2010 to 2025). A disorder of the central nervous system characterized by gradual and progressive loss of neural tissue and neurologic function. "While recent studies have reported certain coding and noncoding EIF2AK3 SNVs as genetic risk factors in several neurodegenerative diseases, including AD and PSP, this is the first study to demonstrate an association between multiple coding and noncoding EIF2AK3 SNVs and cognition in PWH." (PMID 38789639, 2024).
metabolic disease (16 papers, 2013 to 2025). A congenital disorder (due to inherited enzyme abnormality) or acquired (due to failure of a metabolically important organ) disorder resulting from an abnormal metabolic process. "TMAO stimulates the transcription factor FoxO1, which is associated with metabolic disease, in the liver by interacting with the endoplasmic reticulum PKR-like eukaryotic initiation factor 2α kinase PERK (EIF2AK3), serving as a receptor." (PMID 37759983, 2023).
skeletal dysplasia (13 papers, 2013 to 2026). Any Mendelian diseases that affects growth and development of the skeleton. "Case 11 who manifested physical retardation and skeletal dysplasia showed compound heterozygous mutations in EIF2AK3." (PMID 26839896, 2016).
adenocarcinoma (6 papers, 2015 to 2023). A common cancer characterized by the presence of malignant glandular cells. "We found that EIF2AK3-rs6750998 was only correlated with a decreased risk of adenocarcinoma (p < 0.0016)." (PMID 35923704, 2022).
genetic disease (4 papers, 2009 to 2023). "Mutations in Perk (EIF2AK3) underlies the complex genetic disorder of the Wolcott Rallison syndrome, which includes permanent neonatal diabetes (PND), exocrine pancreas deficiency, growth retardation, hepatic dysfunctions, and skeletal dysplasias." (PMID 19732428, 2009).
autosomal recessive disease (2 papers, 2010 to 2021). Autosomal recessive form of disease. "As a rare autosomal recessive disease, with no clinical manifestations in parents, genetic counselling can only be proposed to parents of a previous diagnosed WRS child, with confirmed EIF2AK3 mutation." (PMID 21050479, 2010).
EIF2AK3 also shares sentences with these, for which no sentence is quoted: hepatocellular carcinoma (53 papers); colon carcinoma (50); pancreatic cancer (47); Obesity (38); prion disease (36); Insulin resistance (34); ovarian carcinoma (34); prostate carcinoma (34); glioblastoma (33); Parkinson disease (26); neuroblastoma (24); Cognitive impairment (21); cardiac hypertrophy (18); liver cancer (18); Sepsis (17); frontotemporal dementia (16); Hypertension (16); cervical cancer (15); multiple myeloma (14); steatosis (14); squamous cell carcinoma (13); type 2 diabetes (13); Cerebral ischemia (12); triple-negative breast carcinoma (12); bladder cancer (11); heart failure (11); ischemia (11); renal fibrosis (11); amyotrophic lateral sclerosis (10); diabetic cardiomyopathy (10).
A further 367 diseases each share a sentence with EIF2AK3 in 10 papers or fewer.